CGAS (cyclic GMP-AMP synthase)
Diseases named in the same sentence as CGAS in open-access papers (continued):
Sharing a sentence is not in itself a finding about the gene and the disease.
viral infection (continued). "In addition, cGas−/− cells or mice are more susceptible to a wide range of viral infections, many of which do not produce a classical ‘trigger’ of this pathway." (PMID 36379959, 2022). "This identification of cGAS as a palmitoylated protein expands the knowledge of the role of palmitoylation in regulating protein function, which might provide new targets for drug development against viral infections and autoimmune diseases." (PMID 36591232, 2022). "Furthermore, viral infection also induces mtDNA release, for example, cGAS senses the virus by detecting the release of mtDNA during dengue virus infection, and viroporin activity of influenza virus M2 is essential for mtDNA release into the cytosol in a MAVS-dependent manner." (PMID 35185917, 2022). "However, compared with its functions in viral infection, the cGAS-STING signaling pathway in bacterial infection is more complex and diverse since the protective and detrimental effects of type I IFN (IFN-I) on the host depend on the bacterial species and infection mode." (PMID 35095914, 2021). "However, whether cia-cGAS can bind to cGAS under viral infection conditions and participate in the regulation of antiviral natural immune responses needs to be further investigated." (PMID 34899698, 2021). "We can speculate that the inhibition of cGAS–STING in multiple organs may reduce the severity of some diseases; however, it may also significantly downregulate innate immune function, leading to an increased risk of viral infection and tumor invasion." (PMID 34906241, 2021). "Similarly, although miR-23 has been reported to inhibit cGAS synthesis in other cell types, virus infection of HT1080 cells did not cause a reduction of cGAS." (PMID 34591940, 2021). "Interestingly, viral infection has been demonstrated to induce cell apoptosis, and the activation of apoptotic caspases can cleave cGAS, MAVS, and IRF3, which may be an important mechanism for viruses to evade immune surveillance." (PMID 34718659, 2021). "Given that DNA-PK inhibits the cGAS-STING signaling axis and DNA-PK partly localizes in the cytoplasm, we assessed whether DNA-PK associates with these key signaling components upon virus infection." (PMID 33273464, 2020). "During viral infections, pathogen-associated molecular patterns (PAMPS) are recognized by innate immune sensors, i.e., toll-like receptors (TLRs), retinoic acid-inducible gene I (RIG-I), and cyclic GMP-AMP synthase (cGAS), triggering a rapid IFN type I response against infection." (PMID 32357520, 2020). "Thus, it is possible that bats may use two mechanisms to suppress the cGAS-STING pathway to make the host become more tolerant of viral infection." (PMID 31719180, 2019). "JAK-STAT pathway is downstream of the IFN signaling pathway co-activated by RLRs and cGAS/STING, major PRRs that recognize viral infection." (PMID 40920886, 2025). "Upon viral infection, DNA damage triggers the translocation of nuclear poly(ADP-ribose) polymerase 1 (PARP1) to the cytoplasm, interacts with cGAS, and catalyzes PARylation at D191, thus blocking dsDNA binding." (PMID 40470467, 2025). "cGAS-STING signaling is activated during the innate immune response to cytosolic dsDNA generated by chromosomal instability and viral infection." (PMID 41436729, 2025). "This review has outlined age-related differences in the T1IFN pathway, regulated by the cGAS-STING pathway, and response to viral infection." (PMID 41181142, 2025). "The cGAS-STING signal recognizes inherent and extrinsic nucleotides and has a crucial effect on viral infections, bacterial infections, organ fibrosis, autoimmune diseases, and cancer." (PMID 40296918, 2025). "Since the discovery of the cGAS-STING pathway, cGAS has emerged as the primary cytoplasmic DNA sensor, playing a pivotal role in responding to various viral infections." (PMID 40704898, 2025). "Among these receptors, the cGAS-STING pathway, plays a significant role in the innate immune response to viral infections." (PMID 40552037, 2025).
viral infection (continued). "Upon a viral infection, such as COVID-19, IFN-I is produced when viral RNA or DNA activates the intracellular cytosolic nucleic acid sensors like RIG-I and cGAS." (PMID 41372563, 2025). "The cGAS-STING signaling pathway is not only an evolutionarily conserved defence mechanism against bacterial and viral infections but it also alerts from genotoxic and mitochondrial stresses which evoke a leakage of dsDNA into the cytoplasm." (PMID 40542276, 2025). "Targeting the ubiquitination of the cGAS-STING pathway holds significant potential in the treatment of autoimmune diseases, cancer, and viral infections." (PMID 40028324, 2025). "In recent years, as a hot signaling pathway, the cGAS/STING signaling pathway play an important role in bacterial infection, viral infection, immune diseases, and inflammatory diseases." (PMID 40463371, 2025). "HPV16 oncogene E7 can inactivate the cGAS-STING signaling pathway, impairing the immune response to viral infection." (PMID 39295867, 2024). "The cGAS-STING signaling pathway plays a critical role in innate immunity and defense against viral infections by orchestrating intracellular and adaptive immune responses to DNA." (PMID 39295867, 2024). "cGAMP, the second messenger of the cGAS-STING pathway, is critical for this host innate immune responses against viral infections." (PMID 38408104, 2024). "Cytoplasmic DNA and micronucleus generated by DNA damage can be recognized by cGAMP synthase (cGAS), thus binding and activating STING protein to induce interferon, mimicking viral infection." (PMID 39033176, 2024). "cGAS, the synthase for the second messenger cyclic GMP-AMP, can detect exogenous and endogenous double-stranded DNA after bacterial and viral infections." (PMID 38169382, 2024). "Recently, an interesting study showed that the gut microbiota can mediate peripheral cGAS-STING activation, which promotes host resistance to systemic viral infections." (PMID 38426093, 2024). "Intriguingly, PP1’s role in the cGAS-STING pathway, which is activated by cytosolic DNA (self and invaded viral or microbial) needs to be further explored in the context of viral infection." (PMID 38267954, 2024). "Integrated omic and functional analyses identify the cGAS-STING pathway regulating various host cellular responses and controlling viral infections." (PMID 38426093, 2024). "Upon infection with DNA viruses, the viral DNA can be sensed by the host cytosolic DNA sensor cGAS, initiating a series of antiviral signaling pathways that result in the induction of IFN-β and ISG expression to combat viral infections." (PMID 39346919, 2024). "In this paper, we primarily delve into the RNA virus-derived components regulate the cGAS-STING signaling pathway and explore the therapeutic potential of targeting this pathway in virus infections." (PMID 38693578, 2024). "By outcompeting cGAS in dsDNA binding, BAF inhibits the STING pathway, making the host cell permissive to viral infection." (PMID 38675916, 2024). "Recent years have developed inhibitors targeting cGAS‐STING‐TBK1 with benefits in the treatment of inflammation, virus infection, bacterial infection, and cancers." (PMID 39166890, 2024). "However, despite the description of numerous IEIs affecting pathogen and PAMP receptors and their downstream IFN-inducing signaling pathways causing susceptibility to severe viral infections, defects in the cGAS-STING pathway in humans have not been previously reported." (PMID 38277122, 2024). "The TREX1 activity inhibits the recognition of viral DNA by the cyclic GMP-AMP synthase (cGAS) sensor and the activation of the cGAS-STING pathway, resulting in reduced expression of IFN-I, which is essential for the control of viral infections." (PMID 38675842, 2024). "The cyclic GMP-AMP synthase-stimulator of interferon genes (cGAS-STING) pathway is an intracellular DNA sensing pathway and integral innate immune defense mechanism to viral infection or cellular transformation." (PMID 37993280, 2023).
viral infection (continued). "As expected, the viral fluorescence intensity in cGAS OE and STING OE cells was significantly lower than that in control TB1 Lu cells 12 h and 24 h after viral infection." (PMID 37744905, 2023). "Our findings are essential for understanding the molecular mechanism of porcine cGAS–STING pathway and laying a foundation to formulate future therapeutic strategies against porcine viral diseases." (PMID 37660925, 2023). "SELENOK is upregulated during viral infection and enhances STING oligomerization to facilitate the activation of the cGAS-STING pathway and suppress viral replication." (PMID 37023217, 2023). "In the late phase of a viral infection, SUMO-specific protease 2 (SENP2) deSUMOylates cGAS, leading to cGAS degradation through the ubiquitin-proteasomal or chaperone-mediated autophagy pathways." (PMID 36964253, 2023). "In recent years, researches on the cGAS-STING pathway have focused on the role of this pathway in various aspects such as tumor immunity, viral infection, inflammation, and aging." (PMID 37600809, 2023). "cGAS pulled down 2C in SVV-infected cells, and 2C reversely immunoprecipitated cGAS as well, suggesting that SVV 2C protein interacted with cGAS in the context of viral infection." (PMID 36745686, 2023). "Chromosomal segregation errors caused by CIN at the early stages of tumorigenesis activate the cGAS-STING pathway, which functions as an innate cellular defense against viral infection." (PMID 36569844, 2022). "To serve as a reference, we also included WT MEF cells that have an intact cGAS/STING pathway in the transfection-then-infection experiment, and we detected viral infection among WT MEFs, albeit at very low levels." (PMID 35477320, 2022). "In irradiated tumors and viral infections, IFN-I is induced by cytosolic DNA that stimulates cGAS to produce cGAMP, leading to STING activation." (PMID 36077747, 2022). "However, the function of nuclear cGAS in host defense and viral infection is unknown." (PMID 35538147, 2022). "It was initially identified as a DNA sensor that controls viral infection via inducing IFN response, which requires cGAS to synthesize the 2’3’-cGAMP, recognized as an endogenous massager for STING signaling." (PMID 35902564, 2022). "Intracellular recognition of dsDNA by D. melanogaster cGAS-STING induces NF-κB and is required to restrict viral infection." (PMID 36196535, 2022). "Collectively, our study suggests that HSV-1 infection leads to cGAS release from the chromatin tethering; in turn, the nuclear soluble cGAS senses viral DNA and activates type I IFN to suppress viral infection." (PMID 35538147, 2022). "The absence of the N-terminus results in cytoplasmic localization of cGAS and higher basal levels of IFN; however, it also has a weaker response to viral infection." (PMID 36231111, 2022). "An increasing number of studies on the activation of type I IFNs response by viral infection have focused on the cGAS–STING axis, and recent studies have shown that Ca2+ and related signaling proteins regulate cGAS–STING." (PMID 35859744, 2022). "In uninfected cells or during the early stages of viral infection, the ubiquitin ligase TRIM38 targets cGAS to SUMOylate and activates cGAS; in the late stage of infection, SENP2 mediates the deSUMOylation of cGAS to prevent its overactivation." (PMID 36591232, 2022). "Interestingly, a study found that after cells were transfected with foreign plasmids, the ability of host cells to prevent viral infections improved, suggesting that activation of cGAS-STING signaling may ready the cell for subsequently fighting viral infections." (PMID 35185917, 2022). "Based on these mechanistic investigations, the team of Zhijian James Chen and Blossom Damania reviewed the roles of the cGAS-STING pathway in autoimmune, inflammatory disease, and virus infection, respectively." (PMID 35720348, 2022).
viral infection (continued). "This study describes a redundant strategy employed by BPV to thwart cGAS-STING-mediated host innate immune responses, leading to abnormal cellular antiviral defence, in a spontaneous model of viral disease in cattle." (PMID 36311756, 2022). "p62 has been reported to control IFN antiviral responses by promoting autophagic degradation of several key factors in the IFN pathway, including RIG-I, cGAS, MAVS, and IRF3 during viral infection." (PMID 35865923, 2022). "The membrane localization of cGAS is important in distinguishing between endogenous and exogenous DNA, and consequently in the production of type I IFN in response to viral infection." (PMID 35458396, 2022). "The most popular recent pathway is the cGAS-STING pathway, which consists mainly of cGAS and STING, activating the downstream IFN response to protect the host from viral infection." (PMID 35812373, 2022). "Moreover, recent studies suggest that recruitment of TBK1 to STING may perform a more significant role in antagonist virus infection and restrict oncogenesis, which expands the horizon of cGAS-STING axis function besides IRF3 and nuclear factor-κB (NF-κB) signaling." (PMID 34966372, 2021). "The cGAS/STING pathway stimulates type-I IFN during DNA and RNA viral infections, an essential factor in resisting viral infections." (PMID 34768911, 2021). "The cyclic GMP-AMP synthase (cGAS) and its downstream effector pathway, STING, activates the innate immune response in response to viral infection." (PMID 34320035, 2021). "cGAS-STING signalling in particular has garnered attention, stimulating the innate immune system in response to both viral infection and DNA damage." (PMID 33203188, 2020). "cGAS is an important cytosolic sensor for DNA, and the cGAS-STING pathway is very important for host defenses against viral infections." (PMID 33392287, 2020). "The study also found that the SUMO1 specific peptidase 2 (SENP2) deSUMOylates cGAS and STING at the late phase of viral infection or DNA stimulation, which conditions them for subsequent degradation by the ubiquitin-proteasomal or chaperone-mediated autophagy." (PMID 33105828, 2020). "Recent studies of cGAS-STING signaling in insects have demonstrated that Drosophila STING drives NF-κB and autophagy signaling to restrict viral infection." (PMID 33191912, 2020). "An increasing amount of evidence has shown that post-translational modifications, such as phosphorylation and ubiquitination, directly or indirectly modulate the cGAS/STING pathway and significantly affect viral infections." (PMID 31849849, 2019). "PRRs that detect viral infection can be classified into four families: TLRs, RLRs, AIM2-like receptors (ALRs) and the cGAS-STING sensors." (PMID 31426357, 2019). "Answers to these questions and others will further expand our understanding of how the cGAS–STING pathway deploys immune defenses to detect and eliminate viral infection and how viruses evade or inhibit activation of this pathway." (PMID 30114241, 2018). "The knockdown of cGAS or STING completely abrogated IFNβ release and Ifnβ1 and Mx1 gene expression induced by viral infection or 8GyX3 treatment of TSA cells in vitro." (PMID 28598415, 2017). "In addition to viral infection, chemotherapeutic agents such as cisplatin, etoposide, and chitosan, induce oxidative DNA damage that promotes self-DNA leakage from the nucleus and mitochondrion, and therefore trigger cGAS-STING-mediated antitumor immune response." (PMID 29202128, 2017). "Herein, we show that EMCV infection reduces the expression of cGAS and STING proteins, and its 2C protein significantly suppresses the production of IFN-β triggered by poly(dA:dT) or viral infection, as well as the mRNA expression of interferon-stimulated genes." (PMID 42043227, 2026).
viral infection (continued). "Through a combination of RT-qPCR and luciferase reporter assays, we demonstrate that E1 suppresses the production of interferons and interferon-stimulated genes triggered by viral infections and the activation of RIG-I/MDA5-MAVS, TLR3-TRIF, cGAS-STING, and JAK-STAT pathways." (PMID 40330484, 2025). "Once a viral infection has been established, intracellular nucleic acid sensor molecules, including cyclic GMP-AMP synthase (cGAS) and retinoic acid-inducible gene-I (RIG-I), recognize virus-derived double-stranded DNA (dsDNA) and double-stranded RNA (dsRNA), respectively, in the cytoplasm." (PMID 40807684, 2025). "The review aims to provide a comprehensive overview of the ubiquitination processes involved in the cGAS-STING pathway and their roles in various diseases, providing significant therapeutic insights for autoimmune disorders, cancer and viral infections, among other diseases." (PMID 40028324, 2025). "Studies have found that interfering with SPSB3, a cGAS substrate receptor, to regulate the degradation of nuclear cGAS can activate the IFN-1 signaling pathway, providing new insights and potential therapeutic avenues for combating viral infections." (PMID 41226461, 2025). "The cGAS-STING signaling pathway is a critical component of the innate immune response that helps, detect and defend against viral infections and DNA pathogens.The innate immune system is the body’s initial defence against invading pathogens (Akira, Uematsu & Takeuchi, 2006)." (PMID 40552037, 2025). "Interestingly, after virus infection in mice, Piezo1−/− mice presented reduced TLR9, cGAS, STING and IRF3 expression in macrophages in the BALF." (PMID 39890818, 2025). "During the activation of the cGAS-STING signaling pathway, cytoplasmic IRF7 undergoes dimerization and translocation into the nucleus, facilitating the transcription of the IFN-β gene to counteract viral infection." (PMID 40704898, 2025). "Bacteria of microbiota (e.g., Vibrio cholera and Bdellovibrio bacteriovorus) possess enzymes similar to the mammalian cyclic GMP-AMP synthase (cGAS), which can synthesize cyclic dinucleotides (CDNs), including cyclic GMP-AMP (cGAMP) to protect bacteria against viral infection." (PMID 40872922, 2025). "Unlike cGAS activation by exogenous nucleic acids during viral infection, autoimmune diseases are characterized by self-nucleic acid leakage." (PMID 41583428, 2025). "In the context of viral infections, NADases such as CD38 or PARPs may promote NAD decline, facilitating leakage of mtDNA and amplifying the cGAS‐STING response." (PMID 40519092, 2025). "Importantly, TRIM56 plays a crucial role in antiviral defense by either directly inhibiting viral infection or regulating the host antiviral type I IFN response through modulating the toll-like receptor (TLR) and cGAS-STING signaling pathways." (PMID 39747662, 2025). "Furthermore, gigaxonin mediates the ubiquitination of both cGAS and TREX1 by the cullin‐RING E3 ubiquitin ligase 3 (CRL3) complex, triggering cGAS activation upon virus infection and TREX1 degradation in the steady state." (PMID 40936183, 2025). "In addition, the interaction between the TBK1-IRF3-IFN pathway downstream of cGAS-STING and autophagy in viral infections is very complex." (PMID 38426093, 2024). "Triggered by various stimuli, including viral infections and nucleic ligands, IFN-1 production involves PRRs and cytoplasmic sensors like cGAS, activating transcription factors such as IRFs and NF-κB, culminating in IFN-α and IFN-β production and downstream signaling via IFNAR1/2 receptors." (PMID 39061208, 2024). "Here, we outline recent insights into cGAS-STING in regulating type I interferon, inflammation, oxidative stress, autophagy and endoplasmic reticulum stress and discuss their interactions with viral infections." (PMID 38426093, 2024). "Consequently, cGAS evades p62-mediated autophagic degradation and can stimulate type I IFN signaling after viral infection." (PMID 38660307, 2024).